RNU6-609P (RNA, U6 small nuclear 609, pseudogene)
Gene: Small nuclear RNA gene on chromosome 1 (200,014,689 to 200,014,795, reverse strand). Ensembl gene ENSG00000202329.
Homologues: Orthologues: chimpanzee U6 (97% identical), macaque U6 (94% identical), guinea pig U6 (91% identical), pig U6 (91% identical), dog U6 (88% identical), guinea pig U6 (85% identical), mouse Gm24707 (85% identical), rat LOC120095814 (80% identical), pig U6 (78% identical). Paralogues in human: RNU6-1011P (90% identical), RNU6-25P (90% identical), RNU6-33P (90% identical), RNU6-36P (90% identical), RNU6-38P (90% identical), RNU6-468P (90% identical), RNU6-842P (90% identical), RNU6-1 (89% identical), RNU6-1060P (89% identical), RNU6-1158P (89% identical), RNU6-11P (89% identical), RNU6-15P (89% identical), and 1287 more.